FOXM1 (forkhead box M1)
Diseases named in the same sentence as FOXM1 in open-access papers (continued):
Sharing a sentence is not in itself a finding about the gene and the disease.
tumor (continued). "Recently, a growing number of studies have described FOXM1 as a key oncogenic transcription factor, as it can promote tumor progression." (PMID 33968339, 2021). "In the current study, we verify that FOXM1 is a downstream target gene of miR-877-5p and is subject to the positive regulation of circPIK3CA in the tumor microenvironment (TME) of GBM." (PMID 35004326, 2021). "In general, the expression of miR-6868-5p is downregulated in CRC, and downregulation of miR-6868-5p inhibits tumour angiogenesis through inhibition of FOXM1; FOXM1 can also inhibit miR-6868-5p expression through promoter histone methylation." (PMID 33865381, 2021). "FoxM1 induces the expression of genes involved in cell proliferation, therefore down-regulation of FoxM1 inhibits tumor growth." (PMID 34758842, 2021). "Recent studies have shown that miR-6868-5p is able to inhibit tumour angiogenesis by inhibiting the FOXM1-IL-8 axis." (PMID 33865381, 2021). "FOXM1 also weakened the promotion of T cell proliferation and depleted IL‐12 p70 in tumor‐bearing mice." (PMID 34489925, 2021). "FOXM1 is a Forkhead transcription factor that regulates G2-specific gene expression, promotes cell proliferation and contributes to tumour progression." (PMID 34728711, 2021). "Consistently, the combination therapy with both abemaciclib and merestinib decreased FOXM1 to the lowest level among the four treatment groups and inhibited tumor growth significantly in hHGF-knock-in NSG mouse models." (PMID 33806615, 2021). "Linked to a proliferative, invasive, and metastatic phenotype in HCC, we further detected high levels of expression of factors essential for tumor progression such as FoxM1, C-met, and Inppl1 in AS-30D cells compared with normal hepatocytes." (PMID 34737944, 2021). "CDK4/6 inhibitors function as ATP competitive inhibitors, while they intervene in the phosphorylation and inactivation of retinoblastoma, a key tumor suppressor fundamental in cell cycle and the inactivation of FOXM-1." (PMID 33732735, 2021). "An absence of FOXM1 correlates to significantly longer survival in GBM patients, all of which indicates a potential connection between FOXM1 and tumor progression." (PMID 34948433, 2021). "The expression of FOXM1 was increased while that of Linc-ROR, LMO4, and Ki-67 was decreased in the tumor tissue of the mice in the oe-FOXM1 + sh-Linc-ROR group when compared with the oe-FOXM1 group." (PMID 34447693, 2021). "FOXM1 has differential expression in patients with different tumor stages, genders, races, and molecular subtypes." (PMID 33892811, 2021). "The reduction in FOXM1 and N-Myc levels is the critical mechanism by which depletion of Aurora-A inhibits tumour proliferation, as confirmation of its interdependence with the two oncoproteins." (PMID 33981003, 2021). "As FOXM1 is over-expressed in a majority of human malignancies, it is also a target of regulation by multiple tumor suppressors." (PMID 35004326, 2021). "Tumor load in the animals bearing circPIK3C2A-KD and FOXM1 FOXM1-OE) con-transfected cells was higher than the circPIK3C2A-KD group." (PMID 35004326, 2021). "Activation of the uPA/uPAR axis in PDA tissues and cell lines correlated with an increase in FOXM1, and silencing of FOXM1 suppressed uPA and uPAR expression, angiogenesis and tumor growth both in vitro and in vivo." (PMID 33804240, 2021). "We proved that avasimibe alone inhibited cell viability and tumor growth of human CCA cells by targeting the FoxM1/AKR1C1 signaling pathway." (PMID 34127944, 2021). "Here we show that FOXM1 regulation by thiostrepton decreases tumor cell survival in addition to carboplatin or olaparib treatment in individual cases." (PMID 33668819, 2021). "The predicted activities of motifs associated with EPAS, BCL3, FOXM1, and TBL1XR1 were higher in ILC than in the non‐ILC tumor cells." (PMID 33616307, 2021). "The transcription factor FOXM1 is a key regulator of tumor survival affecting multiple cancerogenic target genes." (PMID 33668819, 2021).
tumor (continued). "FOXM1expression was substantially elevated in LUAD, the expression of FOXM1 was significantly elevated in LUAD patients than normal controls based on tumor grade." (PMID 35211508, 2021). "Taxanes are another class of anticancer drugs that exhibit decreased efficacy against tumor cells with high FOXM1 levels." (PMID 34262016, 2021). "The administration of CDDP also significantly decreased the tumor volumes in mice injected with CtBP1-KD or FOXM1-KD cells when compared with mice injected with MG63-R1 orMG63-R2 cells." (PMID 33391445, 2021). "Considering the pivotal involvement of FoxM1 up-regulation during HCC tumor development and progression, we sought to gain insight into the possible regulatory effect of Artemisinin on FoxM1." (PMID 34900697, 2021). "In vitro and in vivo experiments revealed that reduced FOXM1 level can rescue the effects induced by increased circular PVT1 on tumor viability." (PMID 33391456, 2021). "Deletion of Foxm1 prior to or following a tumor induction stimulus in mice decreased both the number and size of tumors in the lung, liver, and colon." (PMID 34205406, 2021). "By informatics analysis, we identified three tumor suppressor genes: DACH1, PCDH10 and SMAD4, all of which were negatively associated with FOXM1 and validated as functionally relevant targets of miR-552." (PMID 33867818, 2021). "Positive DKK1 and FOXM1 staining were seen in 29/38 (76.3%) and 33/38 (86.8%) cases, respectively, while both proteins were minimally detected in the non-tumor regions of pancreatic ducts under our staining conditions." (PMID 34117362, 2021). "Since miR-134 targets and inactivates KRAS, Nanog mRNA, HNF4α, EGFR, ITGB1, and FOXM1, it also inhibits tumor invasion and metastasis." (PMID 33331954, 2021). "Subsequently, cell viability and colony formation assays were performed to examine the involvement of FOXM1 in the effect of LECT2 on tumor proliferation." (PMID 33937262, 2021). "Once glycolysis is activated, induced expression of FOXM1 strengths the squamous PDAC phenotype by (over)stimulation of tumor hypoxia and the EMT." (PMID 34503261, 2021). "Cumulatively, our results indicated that FoxM1 silencing in resistant HCC cells effectively sensitized them to the tumor suppressive activities of Artemisinin, reflected by their attenuated neoplastic transformations and enhanced apoptosis." (PMID 34900697, 2021). "FOXM1 strongly enhances the nuclear translocation of β-catenin, which is required for the tumor-initiating capacity of glioblastoma cells in vivo." (PMID 34298659, 2021). "Increasing the level of FOXM1 is related to some clinicopathological characteristics, such as tumor size, TNM stage, lymphatic metastasis, and distant metastasis." (PMID 34252882, 2021). "We also conducted rescue assays to validate circular PVT1 impeded tumor growth by targeting to FOXM1." (PMID 33391456, 2021). "AKR1C1 was a promising predictor for tumor recurrence and overall survival and correlated significantly with FoxM1 expression in CCAs." (PMID 34127944, 2021). "FoxM1, belonging to the Fox transcription factor family, was related to tumor formation in multiple cancers." (PMID 33882027, 2021). "It was showed that overexpression of STMN1 in FoxM1-knockdown cells partially rescues the tumor growth in nude mice." (PMID 33526768, 2021). "FOXM1 is a transcription factor necessary for tumor proliferation, and its expression level is often related to the degree of malignant progression of tumors." (PMID 33502747, 2021). "FOXM1 plays a critical role in each of the steps of tumor initiation, progression, metastasis, and treatment." (PMID 33314660, 2021). "FoxM1 is reported as an important effector in response to several oncogenic signal pathways and also facilitates in cell growth, angiogenesis, tumor invasion, DNA damage repair, senescence and cell cycle." (PMID 33526768, 2021).
tumor (continued). "Inhibition of USP5 significantly decreased tumor growth and correlated with downregulation of FOXM1, suggesting that USP5 plays a critical role in tumorigenesis and progression of PDA by stabilizing the FOXM1 protein." (PMID 33804240, 2021). "Mice bearing USP28-silenced cells showed a notable decrease in tumour weight and volume; whereas, simultaneous overexpression of FOXM1 fully abolished the anti-tumour effect of USP28-knockdown." (PMID 34584067, 2021). "FOXM1 inhibition was therefore shown to counteract this tumor adaption of increased HR and to downregulate BRCA1/2 and RAD51." (PMID 33668819, 2021). "In particular, a very recent study demonstrated that FOXM1 physically interacts with the architectural transcription factor HMGA1 to promote tumor angiogenesis cooperatively both in vitro and in vivo models." (PMID 33479222, 2021). "There are three main subtypes of FOXM1, of which FOXM1B is closely related to tumor growth and metastasis." (PMID 33968766, 2021). "Although earlier studies have showed that FOXM1 contributes to the progression of malignancy in multiple tumor types, the mechanism by which FOXM1 simultaneously triggers metastasis and chemoresistance remains poorly understood in CRC." (PMID 33291076, 2020). "Inhibition of USP39 by siRNA has downregulated FOXM1 and in turn led to tumor volume reduction in xenograft model of HCC." (PMID 33680951, 2020). "Tumor volume and weight were conspicuously blocked in sh-circ-FOXM1 groups compared to sh-NC control groups." (PMID 32183822, 2020). "Cell migration and invasion are important processes in tumor metastasis and FoxM1 is known to control these processes." (PMID 32429421, 2020). "FOXM1 is a master transcription factor that promotes tumorigenesis and tumor progression mainly by stimulating expression of many genes involved in the cell cycle progression." (PMID 33124191, 2020). "In MCF-7 cell lines, combination therapy enhanced the downregulation of essential components of the cell cycle (HMMR, AURKB, BIRC5) that control proliferative activities and tumour growth alongside downregulation of the anti-senescence markers FOXM1 and E2F1." (PMID 32787886, 2020). "Further in vitro and in vivo study found that the FOXM1 inhibitor thiostrepton inhibited PTC cell line xenograft tumor growth and this was accompanied by downregulation of FOXM1, MMP9, and MMP2." (PMID 32603365, 2020). "Overall, this suggests the clear oncogenic role of FOXM1 in maintaining tumor invasion and metastasis." (PMID 33292277, 2020). "And we found that while knocking down FOXM1, the tumor growth was suppressed, and at the same time, the expression of TPX2 was also decreased in vivo." (PMID 32723329, 2020). "Here we show that the tumor suppressor RASSF1A exerts many of its effects through suppression of FOXM1 and increasing FOXO3A activity." (PMID 32967092, 2020). "FOXM1 plays important roles in tumor initiation and progression, angiogenesis, drug resistance, and metastasis of many cancers, including CRC." (PMID 33419310, 2020). "The upregulated FOXM1 induces transcription of genes involved in cell proliferation, resulting in tumor growth." (PMID 33142744, 2020). "FOXM1 is a member of the Forkhead box (Fox) transcription factor family and has critical functions in tumor development and progression." (PMID 31974380, 2020). "As a result, the repression of FOXM1 by inhibitors of H3K79me2 reduced immunosuppression in the TME and caused xenograft CT-26 tumor regression." (PMID 33419310, 2020). "FOXM1 is involved in translocation of β-catenin to the nucleus where it functions as a transcription factor for tumor progression." (PMID 33142744, 2020). "FOXM1 staining was positive in 38 out of 46 tumor tissues (82.6%) and was observed primarily in the nucleus." (PMID 33142744, 2020). "Consistently, ectopic expression of FOXM1 in GSCs expressing shSATB2 restored GBM tumor growth and attenuated the increased survival of mice bearing the GSC‐derived GBMs." (PMID 33124191, 2020).
tumor (continued). "Forkhead box protein M1 (FOXM1), a transcription factor with a “winged helix” DNA-binding domain, plays a significant role in tumor progression through cell proliferation, tumor invasion, migration, and angiogenesis." (PMID 31987036, 2020). "The question remains as to how FOXM1 regulates tumor cell growth, invasion and the formation of VM structures in ESCC?" (PMID 32035486, 2020). "Previous studies have found OTS514 has anticancer effects in TOPK expressing tumours by regulating FOXM1 and MELK expression." (PMID 32960500, 2020). "Upon TGF-α induction, TESC is upregulated and promotes tumor growth through FOXM1-mediated G2/M transition." (PMID 32365487, 2020). "FOXM1 is essential in the regulation of oxidative stress, and its disruption contributes to malignant transformation and tumor cell survival." (PMID 31974380, 2020). "We observed a significant decrease in motility and invasiveness of TNBC cells when treated with these compounds in cell culture, and our in vivo studies revealed that the FOXM1 inhibitory compounds attenuated tumor growth and distant metastasis." (PMID 32961773, 2020). "Results from transwell and scratch wound assays confirmed similar role of FoxM1 on PTTG3P-induced pro-tumor biofunctions." (PMID 33298873, 2020). "Further, orthotopic tumor studies in NOD-SCID-gamma (NSG) mice demonstrate that these compounds reduce FOXM1 expression and suppress TNBC tumor growth as well as distant metastasis." (PMID 32961773, 2020). "Consistently, another report suggested that FOXM1 is essential for carcinogenesis as it controls the expression of 11β-Hsd2, which is important for tumor cell proliferation." (PMID 32629770, 2020). "FOXM1 is critical for tumor progression as it promotes angiogenesis, invasion, metastasis, response to DNA damage as well as resistance to therapeutics that cause genotoxicity." (PMID 33142744, 2020). "Taken together, our data suggested that miR-320d acts as a tumor suppressor in GCA by directly targeting FoxM1 and thus potentially serves as a biomarker for anti-GCA therapy in GCA patients." (PMID 32551039, 2020). "The data above strongly demonstrate that upregulation or downregulation of miR-320d in GCA tumors can significantly influence the FoxM1 level, thus affect tumor growth in tumor-bearing mice." (PMID 32551039, 2020). "Here, we show that the Special AT‐rich Binding Protein‐2 (SATB2), one of crucial NMPs, recruits histone acetyltransferase CBP to promote the FOXM1‐mediated cell proliferation and tumor growth of GBM." (PMID 33124191, 2020). "Here, we found that the FoxM1 silencing inhibited cell growth and invasion, indicating that FoxM1 functions as a tumor promoter in ESCC." (PMID 32035486, 2020). "In lung cancer, MZF1 can upregulate the expression of NKX2-1, which in turn increases the expression of FOXM1 resulting in facilitated tumor growth and invasion." (PMID 31963147, 2020). "Previous studies by other investigators suggest that FOXM1 upregulation promotes tumorigenesis by potentiating tumor cell proliferation." (PMID 32066721, 2020). "In conclusion, we reported a novel signal axis through which Hh signaling regulates tumor growth via FOXM1 and TPX2." (PMID 32723329, 2020). "The Cancer Genome Atlas (TCGA) was used for analyzing the association between FOXM1/PLAU and tumor immune infiltration." (PMID 31949481, 2020). "On the contrary, the FoxM1 mRNA expression level was significantly higher in tumor tissues than in the adjacent normal tissues (P < 0.001)." (PMID 32551039, 2020). "For instance, miR-370 and miR-132 suppress EMT-related processes inhibiting tumor growth and metastasis via targeting fork head box protein M1 (FOXM1) and SRY-box 4 (SOX4), respectively." (PMID 32391253, 2020). "Due to the presence of tumour heterogeneity, FoxM1 was unfortunately present only in the DEG list of GSE4290 and GSE45921, and therefore not in the list of 59 DEGs we finally found." (PMID 32667745, 2020).
tumor (continued). "In human papillomavirus infected cervical cancer, MZF1 induces the expression of another transcription factor, NKX2-1, which in turn upregulates a cancer stem cell regulator FOXM1, resulting in increased tumor growth and invasion." (PMID 31963147, 2020). "OTUB1-mediated deubiquitination of FOXM1 up-regulates ECT-2 to promote tumor progression in RCC, providing a new potential therapeutic target for RCC treatment." (PMID 32257108, 2020). "These multiple levels of control of FOXM1 by FOXO3 emphasise the significance of FOXO3 as a tumour suppressor." (PMID 32372224, 2020). "The IHC analysis of 66 patient samples also confirmed the overexpression of TPX2 and FOXM1 in tumor tissues." (PMID 32723329, 2020). "In oral squamous cell carcinoma, the upregulation of FOXM1 has been shown to correlate with tumor growth, and FOXP3-mediated immune modulation appeared to potentiate the anti-tumor effectiveness of regulatory T cell-based immunotherapy." (PMID 32967107, 2020). "TESC induced by the TGFα/EGFR/signal transducer and activator of transcription 3 (STAT3) signaling pathway promotes cell proliferation and tumor growth in vivo and in vitro by increasing the expression of forkhead box M1 (FOXM1)." (PMID 32708604, 2020). "Using the PDX model, after treatment with gemcitabine, the Western blotting result showed that, tumor tissue with higher expression of FOXM1 presents higher p-P65 and Bcl2 levels and and low levels of Bax expression." (PMID 30782607, 2019). "FOXM1 is a vital regulator of many biological processes, and dysregulation of FOXM1 contributes to carcinogenesis and tumor progression." (PMID 31072351, 2019). "In the present study, we found that bortezomib treatment led to a significant reduction in both mRNA and protein expression of FOXM1, which is very important for tumor malignant behaviors." (PMID 31796105, 2019). "For instance, the natural inhibitor agent thiostrepton blocks the transcriptional activity of FOXM1 by preventing its binding to target sites in target gene promoters, leading to the suppression of tumor growth." (PMID 31072351, 2019). "Compared with those in para-tumor brain tissues, FOXM1 and Survivin IHC staining intensities were markedly increased in tumor tissues, especially in GBMs (P < 0.05 or P < 0.01)." (PMID 31796105, 2019). "One mechanism by which FOXO3A exhibits its tumor suppressive properties is by transcriptionally antagonizing FOXM1." (PMID 30978209, 2019). "Investigating the effects of FOXM1 on DCs in a tumor‐specific environment is an urgently needed and a straight forward approach to determine the role of FOXM1‐mediated tumorigenesis." (PMID 30628173, 2019). "Yes-Associated Protein (YAP) is a known transcriptional coactivator of FoxM1 and it is normally unphosphorylated due to inactivation of the Hippo tumor suppressor pathway in CRC." (PMID 30744076, 2019). "FOXM1 retarded maturation phenotypes of BMDCs, inhibited promotion of T‐cell proliferation, and decreased interleukin‐12 (IL‐12) p70 in tumor‐bearing mice (TBM)." (PMID 30628173, 2019). "The FOXM1 transcription factor stimulates the proliferation of tumor cells during the progression of NSCLC." (PMID 30992007, 2019). "Positive OPN staining was predominantly observed in stromal cells, while positive FOXM1 staining was mainly present in tumor cells." (PMID 30367545, 2019). "FOXM1 is involved in a wide array of biological functions, including cell proliferation, cell cycle regulation, angiogenesis, cell migration, tumor invasion, senescence, DNA damage repair, stem cell expansion, and renewal." (PMID 30628173, 2019). "These FOXM1-transgenic mice display increased growth and higher numbers of tumours compared to wild-type controls." (PMID 30728402, 2019). "In the presented work, we describe a tumor suppressor mechanism of miR-4521 regulating FOXM1 expression in MB." (PMID 31541075, 2019).